MYCN (MYCN proto-oncogene, bHLH transcription factor)
Diseases named in the same sentence as MYCN in open-access papers (continued):
Sharing a sentence is not in itself a finding about the gene and the disease.
tumor (continued). "Their work specifically analyzed anatomic location of tumors along the sympathetic chain and tumor volume, and how these features correlated with genomic aberrations, MYCN amplification, and survival." (PMID 33314708, 2021). "MYCN in turn drives tumor growth, as is shown by reduced tumor size upon treatment with the MYCN antagonist JQ-1, and elicits postnatal NB formation." (PMID 34771690, 2021). "Accordingly, miR-204 was identified as a tumour suppressor and a putative therapeutic agent, since in mouse xenograft experiments, MYCN-amplified cells transduced with an inducible miR-204 construct showed delayed tumourigenesis." (PMID 34445233, 2021). "MYCN amplification in neuroblastoma can therefore induce a dose-dependent increase in the expression of genes with weak MYCN binding sites in their enhancers, thus promoting tumor-specific expression of MYCN target genes." (PMID 34200747, 2021). "Overall, our results demonstrated that restoration of the molecular clock via activation of RORα blocks MYCN-driven tumor growth and lipid metabolism." (PMID 34183658, 2021). "Overexpression of EZH2, which is the catalytic unit of PRC2, was reported in MYCN-amplified NB, potentially silencing genes or networks of genes with a tumor suppressive role." (PMID 33404859, 2021). "Although highly recurrent RB SCNAs—gains on 1q, 2p, 6p; losses on 13q and 16q; and focal MYCN amplification—are well established and documented, these analyses were performed exclusively on tumor tissue from enucleated eyes." (PMID 34283049, 2021). "By array-CGH analysis of the tumor tissue and of the metastatic bone marrow aspirate cells, we found a high-grade amplification of six regions besides MYCN on bands 2p25.3–p24.3." (PMID 34830942, 2021). "Another tumor suppressor function of TRIM32 was defined in its ability to facilitate the proteasomal degradation of MYCN in neuroblastoma cells." (PMID 33802079, 2021). "These latter events in GLI2 and MYCN further support a driver role for these genes in Shh-MB, and are clinically important as their presence in a tumor will likely render them unresponsive to Sonic Hedgehog pathway inhibition using small molecules." (PMID 33741928, 2021). "The regulation of NB cell death by MYCN represents an important aspect, as it directly contributes to tumor progression and therapeutic resistance." (PMID 34011924, 2021). "RMI2 was also reported to act as a tumor promoter by mediating MYCN/PARP DDR signaling pathway in neuroendocrine prostate cancer." (PMID 34408776, 2021). "Subsequently, Rb tumours with mutation of both RB1 alleles and also amplification of MYCN were discovered." (PMID 33670346, 2021). "The amplification of the MYCN gene, coding for the N-Myc transcription factor, is an essential marker correlated with tumor progression and poor prognosis." (PMID 34884931, 2021). "In CB1008, MYCN-regulated genes were significantly enriched towards diagnosis, in agreement with the decrease of MYCN copy number during tumour progression." (PMID 34815394, 2021). "One important function of MYCN in NB is upregulating glutamine transporters, such as ASCT2, thereby promoting glutamine addiction, a hallmark of tumor metabolic reprogramming." (PMID 34011924, 2021). "Amplification of the MYCN gene in tumor cells is generally found in patients with advanced stage tumors, and is associated with rapid tumor progression and a poor prognosis, regardless of the age or stage of the patient." (PMID 33573284, 2021). "Despite increasing evidence on the importance of tumor cell metabolism for cancer progression, only a few studies showed the role of MYCN in the regulation of metabolic processes in RB." (PMID 34680394, 2021). "Tumor maintenance requires constant MYCN expression, while inhibition of its expression leads to aging of tumor cells." (PMID 33430425, 2021). "Selective inhibition of HDAC8 by small-molecule inhibitors kills tumour growth in xenograft mouse models of MYCN-amplified NB." (PMID 34195095, 2021).
tumor (continued). "Rosa26_Alkal2 mice were bred with Th‐MYCN transgenic mice and progeny monitored for tumour development." (PMID 33411331, 2021). "This would permanently fix transient oncogenic signals, perhaps explaining why MYCN-amplified tumours can revert to focally amplified, and focally amplified to non-amplified, during the evolution of the disease." (PMID 34847775, 2021). "MYCN and ALK gains of 3.7 and 2.9, respectively, were detected in a patient with 4 and 3 copies, respectively, as found in matched diagnostic tumor DNA by SNP array analysis." (PMID 34282791, 2021). "All of which reveals a high specific collaboration between MDM2 and MYCN oncoproteins in this tumor." (PMID 34832966, 2021). "Relationships between the five-gene signature risk score and the clinical characteristics of NB patients, including INSS stage, age, MYCN status, tumor histology, tumor ploidy, and race, were analyzed in TARGET data sets." (PMID 34950701, 2021). "It is known that in non-MYCN-amplified NB displaying 5p15 gains, TERT expression increases, functioning in lieu of MYCN amplification to promote tumor progression." (PMID 34830942, 2021). "It is likely that in these tumours, as in other cancers, MYCN reconfigures metabolism to favour aerobic glycolysis and a dependency on the serine-glycine-one-carbon (SGOC) to generate metabolic products starting from serine and glycine amino acids." (PMID 34195095, 2021). "NB patients diagnosed with metastatic disease, or older than 18 months, or when the tumor carries genomic amplification of MYCN oncogene and/or segmental chromosome abnormalities, are considered to be at high risk of death." (PMID 33915956, 2021). "Nevertheless, most NB tumours have substantial nuclear MYCN protein expression and relatively low MYCN mRNA levels, implying an alternative route for the protein stabilization of MYCN in this type of tumour." (PMID 34954904, 2021). "MYCN overexpression and amplification have also been frequently associated with GBM (in about 40% of tumor samples)." (PMID 33585252, 2020). "Treatment with AURKA inhibitors decreases MYCN protein levels resulting in suppression of NB tumor growth, making AURKA a suitable target for MYCN-driven cancers." (PMID 33628735, 2020). "Higher MYCN expression drives the tumor initiation and progression in TH‐MYCN mouse and zebrafish models, suggesting that MYCN is conserved across the species." (PMID 31637848, 2020). "Employing Cox regression models, penalized with Elastic Net and including as covariates again the main prognostic factors in NB, MYCN status (normal or amplified), and patient’s age and tumor stage." (PMID 32295184, 2020). "MYCN in‐activation using anti‐sense RNA molecules led to the regression of tumor formation in an animal model." (PMID 31637848, 2020). "Project HOPE (High-tech Omics-based Patient Evaluation), a clinical study aiming to provide multi-omics data of cancer patients, showed the upregulation of MYCN gene expression in tumor tissues compared to normal tissues in 22% of recruited HCC patients." (PMID 33937011, 2020). "Taken together, our in vivo data demonstrate that only SA progenitors are capable of tumor initiation in the context of MYCN overexpression in the transgenic mice." (PMID 32595833, 2020). "Its deficiency in MB mouse models accelerates the incidence and timing of tumor formation in vivo, possibly affecting multiple targets, among which MycN, frequently amplified in SHH-MB and known to drive GNPC proliferation during medulloblastomagenesis." (PMID 32528946, 2020). "For each of these models, tumor formation was reduced, and survival was significantly increased when Atrx was simultaneously inactivated with elevated MYCN expression." (PMID 32060267, 2020). "More importantly, serum or plasma MYCN copy number quantification by real‐time quantitative polymerase chain reaction (qPCR) was used to predict amplified MYCN of tumor in NB, at different cutoff value." (PMID 32896084, 2020).
tumor (continued). "In these experiments, we demonstrated that local treatment with dinutuximab can decrease orthotopic tumor growth and MYCN expression in a MYCN‐amplified tumor." (PMID 32096344, 2020). "Transcriptome profiling of frozen human liver tissues using microarray showed that MYCN gene expression was low in healthy livers, cirrhotic livers, and adjacent non-tumorous liver tissue, while it was dramatically increased in tumor tissues." (PMID 33937011, 2020). "We previously reported that combined occurrence of MYCN amplification and the ALKF1174L mutation in primary tumours resulted in a very aggressive tumour phenotype in patients." (PMID 31937834, 2020). "Perhaps combinatorial inhibition of the up-regulated targets after 17-AAG treatment would further cripple these malignant, MYCN-amplified cancer cells yielding more significant anti-tumor effects with the combination therapy." (PMID 33569349, 2020). "Unfortunately, in the data sets analyzed stage 4S NB patients with tumor MYCN amplified are only 9 (4 in Kocak-649, 1 in Oberthuer-251, and 4 in SEQC-RPM database respectively), thus preventing survival analysis from being performed." (PMID 32429447, 2020). "Copy number alteration (CNA) analysis from the tumor of Patient 1 using Oncoscan showed a diploid genome with a high-level focal amplification (>20 copies) of the 2p24.2 region harboring the MYCN gene." (PMID 32971811, 2020). "Four-week-old tumor-bearing Th-MYCN+/+ mice were treated with saline or furamidine (10 mg/kg) daily for 10 days and the tumor volume was monitored by ultrasound imaging." (PMID 32415090, 2020). "It has been suggested that this is probably due to a deficiency in HRR associated genes ATM, MRE11A, H2AFX, and CHEK1; such tumours very rarely have concurrent MYCN amplification." (PMID 32577161, 2020). "Real-time PCR was employed to analyze the expression levels of MYCN and miR-98 and the data demonstrated that the expression level of MYCN in tumor tissues was significantly higher than that of normal control tissues (P < 0.001)." (PMID 32788584, 2020). "There is also evidence that PI3K up-regulates the expression of VEGF via MYCN dependent mechanisms in NB and the use of PI3K/mTOR inhibitors suppresses NB tumor progression by regulating MYCN degradation, and through paracrine blockade of angiogenesis." (PMID 32722460, 2020). "Previous animal studies have shown that inhibition of MYCN can lead to accumulation of intracellular lipid droplets in tumour cells." (PMID 32150548, 2020). "The contribution of MYCN to myeloid cells and macrophage tumor infiltration and polarization is less clear." (PMID 33050533, 2020). "MYCN-amplified tumor cells seem to be dependent on VRK1 expression for its exacerbated proliferation, raising the possibility of using VRK1 inhibitors for NB treatment as an alternative to MYCN targeting." (PMID 33233777, 2020). "Hereby, the aim of our study was to predict MYCN amplification status of tumor using plasma cfDNA‐based qPCR from patients with NB." (PMID 32896084, 2020). "Both SF1126 and SF2523, orthogonally hit PI3K and BRD4 signaling, which blocks MYCN expression, activation and promotes MYCN degradation, ultimately leading to reduced tumor growth, angiogenesis and tumor metastasis." (PMID 32722460, 2020). "Recent studies showed that the combination of a bromodomain inhibitor with a CDK7 inhibitor, an AURKA inhibitor or an HDAC inhibitor is significantly more effective in suppressing MYCN-driven NB tumor growth than either drug alone." (PMID 33628735, 2020). "The expression profile of MYCNOS1 implied its oncogenic role, particularly in tumor cells with high MYCN amplification, and suggested functional relevance of MYCN." (PMID 33270844, 2020). "We also demonstrate that MYCN mRNA and N‐Myc proteins are significantly reduced in the tumor of the mice bearing miR‐overexpressing cells, suggesting the tumor suppressor properties of these miRs." (PMID 31637848, 2020).
tumor (continued). "NB cells also drive angiogenesis through the secretion of PDGF and fibroblast growth factors (FGF), the expression of which correlates with the MYCN status and the aggressiveness of the tumor." (PMID 33050533, 2020). "The regressive tumor WT01 carried GLI3 Q1437*, the triphasic WT02 harbored MAX R60Q and MYCN T58M mutations, and the blastemal WT03 showed a heterozygous DIS3L2 deletion and a STK32C V339M mutation." (PMID 31562394, 2020). "MYCN also regulates the expression of a tumor suppressor, Dickkopf‐3 (DKK3), a secreted glycoprotein in culture supernatants, by transcriptionally activating the expression of mir‐92 in NB cells." (PMID 31637848, 2020). "In conclusion, our data demonstrated that miR‐15a, miR‐15b, and miR‐16 act as tumor suppressors by regulating the MYCN pathway." (PMID 31637848, 2020). "Several studies have reported that MYCN overexpression in peripheral neural crest is sufficient to initiate NB in a mouse model, while MYCN downregulation increases differentiation and apoptosis, and represses proliferation and tumor growth in vivo." (PMID 32855766, 2020). "Various signaling pathways including PTEN/PI3K/AKT and RAF/MEK/ERK have been identified which control MYCN stabilization and act as major mediators of uncontrolled tumor growth, angiogenesis, invasion, apoptosis and cellular metabolism in NB." (PMID 33109237, 2020). "Overexpression of MYCN allows it to form heterodimers with MYC-associated protein X (MAX) which permits it to act as a transcriptional factor and support continued tumor growth." (PMID 32726962, 2020). "Inhibition of FACT using the small molecule curaxin compound CBL0137 results in a decrease of MYCN and SSRP1 expression, as well as a markedly reduced NB tumor initiation and progression in the TH-MYCN mice especially when combined with standard chemotherapy." (PMID 33628735, 2020). "Most MYC target genes are regulated in a dose dependent manner and non-MYCN-amplified tumor cells that artificially overexpress MYCN retain their ability of neuronal differentiation." (PMID 33585251, 2020). "Accordingly, analyses of patient-derived tumors revealed higher levels of tumor vascularization in MYCN-A tumors than in MYCN-NA tumors." (PMID 33050533, 2020). "One mechanism of induced tumor development indicates a Lin28B-mediated downregulation of Let-7 which results in high MYCN protein expression suggesting that MYCN is the actual driver of oncogenesis." (PMID 33585251, 2020). "It is purported that this is because PARP inhibitors induce high levels of replication stress in MYCN expressing tumours." (PMID 32577161, 2020). "This expression pattern provided an evidence that tumor of NB located in abdomen highly correlated to heavier tumor burden and high rate of MYCN amplification." (PMID 32896084, 2020). "In the present work, structural features of the interaction between peptide nucleic acid (PNA)-based analogs of the tumor-suppressor microRNA-34a with both its binding sites on MYCN mRNA were investigated." (PMID 33330358, 2020). "NVP-BEZ235, a dual inhibitor of both phosphoinositide 3-kinase (PI3K) and mTOR, promotes the degradation of N-MYC by GSK3β activation and effectively decreases tumor burden in the MYCN transgenic mouse." (PMID 33614505, 2020). "An extensive literature search revealed that the expression of tumor suppressor miR, particularly the miR‐15 family, has a potential connection to MYCN as regards prognosis, acquired resistance, and NB stages." (PMID 31637848, 2020). "Many miRNAs such as miR-34a, miR-375, miR-393-5p and let-7 are found to inhibit MYCN mRNA translation or target MYCN mRNA for degradation to suppress tumor cell growth." (PMID 33628735, 2020).
tumor (continued). "Although, a recent in vitro study found that MYCN expression can enable tumor cells to synthesize glutamine from glucose-derived alpha-ketoglutarate." (PMID 33585251, 2020). "No recurrent fusion has been reported in NB, with the exception of fusions including the NBAS gene in MYCN-amplified tumours." (PMID 33172452, 2020). "This work indicates that ODC mediates an oncogenic function of MYCN that is important in tumor initiation and demonstrates the therapeutic potential of polyamine depletion strategies in NB." (PMID 33628735, 2020). "Ten copies of MYCN were detected in RB775, considered to be low MYCN amplification, whereas other tumor tissues carried about two copies compared with blood DNA." (PMID 33270844, 2020). "Still, tumor cell-intrinsic response patterns as a consequence of MYCN activation under varying nutrient conditions largely remain to be identified." (PMID 32346009, 2020). "Presently, fluorescence in situ hybridization (FISH) is the most accurate way to evaluate status of MYCN amplification of tumor or metastatic bone marrow in NB." (PMID 32896084, 2020). "MYC proteins play an important role in oncogenesis and progression of tumors and many reports have shown that suppression of MYC or MYCN by genetic means results in growth arrest, induction of apoptosis or senescence leading to tumor regression." (PMID 33585252, 2020). "As expected, inhibitors of PI3K destabilize the MYCN protein and suppress tumor growth in the TH-MYCN GEMM NB model." (PMID 33628735, 2020). "The INRG classification takes into account several factors, such as tumor stage and differentiation, patient age, histology, MYCN oncogene status, DNA ploidy, and segmental chromosomal anomalies, in particular chromosome 11q aberration." (PMID 32155795, 2020). "We found that among all data sets we analysed (4 showed in this study), Mps1 overexpression is highly correlated with advanced stages of the tumour and MYCN amplification, which are prediction markers for poor outcomes." (PMID 32686724, 2020). "The inverse correlation between MYCN and DLEU2, the host gene for miR‐15 family, in NB patient tumor samples clearly demonstrate that MYCN regulation is through these miRs." (PMID 31637848, 2020). "MYCN associates with EZH2, a methyltransferase and a member of the polycomb repressor complex 2 (PRC2) to repress the NB tumor suppressor gene CLU through a bivalent modification of the chromatin at the CLU promoter." (PMID 33628735, 2020). "We have previously utilized this strategy to first demonstrate the role of MYCN in Group 3 MB development and subsequently showed that long-term withdrawal of MYCN results in tumor regression and life-long remission." (PMID 33585252, 2020). "Consulting public NB patients’ datasets, we remarked that high CHL1 expression was related to better outcomes and higher survival rates, considering tumor stage, age at diagnosis, and MYCN oncogene amplification." (PMID 33326488, 2020). "In consistence with in vitro results, ARV-825 treatment downregulated BRD4 and MYCN protein expression in xenograft tumor." (PMID 33324552, 2020). "Whole-genome analysis of RB170 tumor tissue and matched germline DNA revealed high MYCN amplification (75 copies)." (PMID 33270844, 2020). "More recently, our group has proved that many of such second generation mTOR inhibitors are indeed successful in inhibiting MYCN-amplified SHH MB tumor models both in vitro and in vivo." (PMID 33585252, 2020). "Our group has recently reported a study on the employment of PNA-based analogs of tumor suppressor miRNA-34a, which showed promising features in terms of stability and cellular uptake, for the targeting of MYCN." (PMID 33330358, 2020).